EIF4BP1 (eukaryotic translation initiation factor 4B pseudogene 1)
Synonyms: formerly EIF4BP
Gene: Transcribed processed pseudogene on chromosome 14 (44,077,534 to 44,077,884, reverse strand). Ensembl gene ENSG00000259019.
Diseases named in the same sentence as EIF4BP1 in open-access papers:
EIF4BP1 is named in the same sentence as 2 diseases in open-access papers, as found by Europe PMC text mining. Sharing a sentence is not in itself a finding about the gene and the disease. The quoted sentences say what the papers report.
acute myeloid leukemia (1 paper, 2023). Acute myeloid leukemia (AML) is a group of neoplasms arising from precursor cells committed to the myeloid cell-line differentiation. "C/EBPγ is especially well-studied in acute myeloid leukemia (AML), where it promotes cancer progression through the upregulation of EIF4BP1." (PMID 36675048, 2023).
EIF4BP1 also shares sentences with these, for which no sentence is quoted: cancer (1 paper).